GABRA3 (gamma-aminobutyric acid type A receptor subunit alpha3)
Description:
Alpha subunit of the heteropentameric ligand-gated chloride channel gated by gamma-aminobutyric acid (GABA), a major inhibitory neurotransmitter in the brain. GABA-gated chloride channels, also named GABA(A) receptors (GABAAR), consist of five subunits arranged around a central pore and contain GABA active binding site(s) located at the alpha and beta subunit interface(s) (By similarity). When activated by GABA, GABAARs selectively allow the flow of chloride anions across the cell membrane down their electrochemical gradient. Chloride influx into the postsynaptic neuron following GABAAR opening decreases the neuron ability to generate a new action potential, thereby reducing nerve transmission.
Synonyms: EPILX2
Tractability: Small molecule: an approved drug acts on it; a structure with a bound ligand is known; a high-quality ligand is known; it belongs to a druggable protein family. Antibody: its Gene Ontology location is reachable by antibodies, with high confidence; UniProt places it where antibodies can reach, with medium confidence; UniProt predicts a signal peptide or a membrane-spanning region; the Human Protein Atlas places it where antibodies can reach. PROTAC: its protein half-life has been measured; a small molecule that binds it is known.
Target class: Ion channel; GABA-A receptor; Ligand-gated ion channel
Safety:
Unwanted effects reported when the protein is acted on. In parentheses: how it was acted on, where the effect was seen, and who reports it.
ataxia (activation, acute dosing; central nervous system, cardiovascular; source: Lynch et al. (2017))
convulsions (inhibition, acute dosing; central nervous system, cardiovascular; source: Lynch et al. (2017))
decreased anxiety (activation, acute dosing; central nervous system, cardiovascular; source: Lynch et al. (2017))
decreased blood pressure (activation, acute dosing; central nervous system, cardiovascular; source: Lynch et al. (2017))
decreased body temperature (activation, acute dosing; central nervous system, cardiovascular; source: Lynch et al. (2017))
decreased cardiac contractility (activation, acute dosing; central nervous system, cardiovascular; source: Lynch et al. (2017))
decreased convulsions (activation, acute dosing; central nervous system, cardiovascular; source: Lynch et al. (2017))
decreased locomotor activity (activation, acute dosing; central nervous system, cardiovascular; source: Lynch et al. (2017))
decreased memory (activation, acute dosing; central nervous system, cardiovascular; source: Lynch et al. (2017))
decreased pain (activation, acute dosing; central nervous system, cardiovascular; source: Lynch et al. (2017))
decreased sleep (inhibition, acute dosing; central nervous system, cardiovascular; source: Lynch et al. (2017))
drug abuse/dependence (activation, acute dosing; central nervous system, cardiovascular; source: Lynch et al. (2017))
increased cardiac output (activation, acute dosing; central nervous system, cardiovascular; source: Lynch et al. (2017))
increased eating (activation, acute dosing; central nervous system, cardiovascular; source: Lynch et al. (2017))
increased respiratory rate (activation, acute dosing; central nervous system, cardiovascular; source: Lynch et al. (2017))
increased sleep (activation, acute dosing; central nervous system, cardiovascular; source: Lynch et al. (2017))
muscle relaxation (activation, acute dosing; central nervous system, cardiovascular; source: Lynch et al. (2017))
Gene: Protein-coding gene on chromosome X (152,166,234 to 152,451,425, reverse strand). Ensembl gene ENSG00000011677.
Subcellular location: Postsynaptic cell membrane; Cell membrane
Subcellular location (Human Protein Atlas): Plasma membrane; Nucleoplasm
Pathways (Reactome):
Neuronal System: GABA receptor activation
Gene Ontology:
Molecular function: GABA-A receptor activity; GABA-gated chloride ion channel activity; protein binding; benzodiazepine receptor activity; extracellular ligand-gated monoatomic ion channel activity; monoatomic ion channel activity; signaling receptor activity; transmembrane signaling receptor activity; transmitter-gated monoatomic ion channel activity involved in regulation of postsynaptic membrane potential
Biological process: chloride transmembrane transport; gamma-aminobutyric acid signaling pathway; inhibitory synapse assembly; synaptic transmission, GABAergic; chloride transport; monoatomic ion transmembrane transport; monoatomic ion transport; regulation of postsynaptic membrane potential
Cellular component: GABA-A receptor complex; dendrite membrane; plasma membrane; postsynapse; postsynaptic membrane; GABA-ergic synapse; membrane; postsynaptic specialization membrane
Homologues: Orthologues: chimpanzee GABRA3 (100% identical), macaque GABRA3 (99% identical), rabbit GABRA3 (97% identical), rat Gabra3 (97% identical), mouse Gabra3 (96% identical), guinea pig GABRA3 (96% identical), pig GABRA3 (86% identical), tropical clawed frog gabra3 (76% identical), dog GABRA3 (55% identical), zebrafish gabra3 (48% identical). Paralogues in human: GABRA1 (66% identical), GABRA2 (66% identical), GABRA5 (66% identical), GABRA4 (53% identical), GABRA6 (53% identical), GABRG1 (41% identical), GABRG2 (39% identical), GABRG3 (39% identical), GABRE (32% identical), GLRA2 (32% identical), GLRA1 (31% identical), GLRA3 (31% identical), and 33 more.
Diseases named in the same sentence as GABRA3 in open-access papers:
GABRA3 is named in the same sentence as 42 diseases in open-access papers, as found by Europe PMC text mining. Sharing a sentence is not in itself a finding about the gene and the disease. The quoted sentences say what the papers report.
breast carcinoma (18 papers, 2016 to 2025). "In a recent study, it is shown that loss of editing in GABRA3 leads to invasive phenotype in breast cancer." (PMID 33062411, 2020). "To further assess the functions of A-to-I-edited Gabra3 in breast cancer cells, we then introduced RNA-edited Gabra3 carrying an A-to-G mutation at the I/M site into MDA-MB-436 cells that endogenously express only unedited Gabra3, and subjected these cells to migration and invasion assays." (PMID 26869349, 2016). "While Gabra3 overexpression promotes breast cancer cell invasion, migration and metastasis, the edited Gabra3 has the opposite effect." (PMID 40507918, 2025). "Conversely, recoding by ADAR1p110 of the GABAA receptor α3 (Gabra3) mRNA, which is highly expressed in the adult brain and breast cancer, suppresses invasion by and metastasis of breast cancer cells." (PMID 39030076, 2025). "A-to-I RNA-edited GABRA3 by ADAR1p110 restrained breast cancer cell invasion and metastasis by inhibiting GABRA3-mediated AKT activation." (PMID 37612540, 2023). "ADAR1-edited Gabra3 was only in non-invasive breast cancer and showed that edited Gabra3 reduced the abundance of wild-type Gabra3 on the cell surface and inhibited AKT activation, thereby suppressing breast cancer cell invasion and metastasis." (PMID 35898396, 2022). "GABRA3 can promote breast cancer cell migration, invasion and metastasis by activating the AKT pathway." (PMID 34277633, 2021). "For example, gamma-aminobutyric acid type A receptor alpha 3 subunit (GABRA3) activates the AKT pathway to promote breast cancer cell migration, invasion and metastasis." (PMID 32346127, 2020). "In breast cancer cell culture and xenograft models, GABRA3 transcripts undergo adenosine to inosine (A-to-I) RNA editing that decreases cell invasiveness vs unedited GABRA3, by inducing intracellular retention of α3 subunit-containing receptors." (PMID 33187258, 2020). "Gabra3 overexpression promotes migration and metastasis of breast cancer cells via activating serine/threonine kinase or protein kinase B (AKT) signaling pathway demonstrated in a mouse orthotopic model induced by MCF7 and MDA-MB-436 breast cancer cell lines." (PMID 29334991, 2018). "Our previous study also confirmed that Gabra3 can promote breast cancer cell migration, invasion and metastasis by activating the AKT signaling pathway." (PMID 29078789, 2017). "Consistent with our previous findings in breast cancer cells, reduced Gabra3 expression levels also led to decreased cell numbers and colony formation ability in AsPC-1 and SW1990 cells." (PMID 29078789, 2017). "We now show that overexpression of Gabra3 promotes breast cancer cell migration, invasion and metastasis." (PMID 26869349, 2016). "Taken together, these results suggested that Gabra3 is both sufficient and required for breast cancer metastasis." (PMID 26869349, 2016). "Using bioinformatic analysis of breast cancer genomics data, we discovered that high expression of Gabra3 is significantly inversely correlated with breast cancer survival." (PMID 26869349, 2016). "A-to-I editing on the GABRA3 transcript results in a single amino acid change in the α3 protein, at the I/M site, which reduces the metastatic potential of breast cancer cells." (PMID 27999332, 2016). "The chloride channel, GABRA3, is both necessary and sufficient for breast cancer invasion and metastasis." (PMID 27999332, 2016). "In paired human breast cancer samples, Gabra3 expression was higher in the metastatic samples than in the matched primary breast cancer samples supporting our TCGA data survival analysis indicating that higher Gabra3 expression correlated with poorer survival." (PMID 26869349, 2016). "We demonstrate that Gabra3 activates the AKT pathway to promote breast cancer cell migration, invasion and metastasis." (PMID 26869349, 2016). "However, an A-to-I RNA-edited form of GABRA3 showed that edited GABRA3 suppresses breast cancer cell invasion and metastasis." (PMID 34277633, 2021).
breast carcinoma (continued). "In addition, our previous study demonstrated that Gabra3 activates the AKT pathway to promote breast cancer cell migration and invasion." (PMID 29078789, 2017). "Importantly, we find an A-to-I RNA-edited form of Gabra3 only in non-invasive breast cancers and show that edited Gabra3 suppresses breast cancer cell invasion and metastasis." (PMID 26869349, 2016). "Our study demonstrates a significant role for mRNA-edited Gabra3 in breast cancer metastasis." (PMID 26869349, 2016). "Here, the authors demonstrated that GABRA3 activates AKT to promote breast cancer cell invasion and that the A-to-I edited form of GABRA3, specifically expressed in noninvasive breast cancers, can suppress the function of wild type GABRA3." (PMID 26869349, 2016). "Combined with two other breast cancer and lung adenocarcinoma studies indicating the influence of Gabra3 on the AKT/mTOR, and JNK pathways, we suggest that the regulatory role of miR-92b-3p in the AKT/mTOR and JNK pathways might be indirect and Gabra3-dependent." (PMID 29078789, 2017). "The expression of edited GABRA3 on the cell surface is reduced in non-invasive breast cancer, which prevents AKT activation and thereby prevents breast cancer cells from migrating, invading, and metastasizing." (PMID 37328893, 2023). "We introduced Gabra3 into human breast cancer MCF7 cells, which express endogenous Gabra3 but at low levels, and subjected these cells to migration and invasion assays." (PMID 26869349, 2016). "GABRA3, a subunit of the GABA receptor, is often highly expressed in brain metastasis and breast cancers." (PMID 26869349, 2016). "However, A-to-I-edited GABRA3 has reduced cell surface expression and suppressed the activation of AKT required for cell migration and invasion in breast cancer metastasis." (PMID 32346127, 2020). "Immunoblotting of Gabra3 in human breast cancer cell lines indicated that it was expressed at various levels in breast cancer cell lines but not expressed in the normal human epithelial cell line HMEL." (PMID 26869349, 2016). "To determine whether Gabra3 is required for breast cancer metastasis, we introduced short hairpin RNA constructs into human breast cancer MDA-MB-436 cells expressing high levels of endogenous Gabra3." (PMID 26869349, 2016). "Importantly, we also show that Gabra3 is highly expressed in breast cancer tissues and cell lines but not in normal breast epithelial cells or normal breast tissue." (PMID 26869349, 2016). "We found RNA editing of Gabra3 only in the non-invasive MCF7 and SKBR3 breast cancer cells but not in the invasive cell lines MBA-MD-231, MBA-MD-436 and MDA-MB-453." (PMID 26869349, 2016).
pancreatic cancer (6 papers, 2017 to 2022). "Among them, miR-92b-3p inhibited the proliferation and invasion of pancreatic cancer cells through the downregulation of GABRA3." (PMID 36497462, 2022). "On the contrary, miR-92b-3p suppresses tumor progression of pancreatic cancer by targeting Gabra3." (PMID 34395434, 2021). "For pancreatic cancer, miR-92b-3p acts as a tumor suppressor by targeting Gabra3." (PMID 32138771, 2020).
glioma (5 papers, 2014 to 2024). A benign or malignant brain and spinal cord tumor that arises from glial cells (astrocytes, oligodendrocytes, ependymal cells). "In patients with lower grade gliomas, GABRA3, GABRB3, GABRG1, and GABRG2, were associated with longer OS." (PMID 38539663, 2024). "Moreover, the loss of editing in GABRA3 was associated with an aggressive phenotype of glioma, promoting migration and invasion." (PMID 35327657, 2022). "We previously reported that high levels of GABRA2, GABRA3, GABRB3, GABRG1, and GABRG2 indicated better prognosis in glioma, and GABRB3 was particularly associated with longer OS in patients with lower-grade gliomas." (PMID 39595908, 2024). "One more differentially edited site in GABRA3 (I342M), detected in this work, has previously been shown to be under-edited in lower grade glioma and glioblastoma." (PMID 35052353, 2021).
lung adenocarcinoma (5 papers, 2016 to 2024). A carcinoma that arises from the lung and is characterized by the presence of malignant glandular epithelial cells. "This confirmed significant association between CT-GABRA3 activation and GABRA3 promoter hypermethylation in lung adenocarcinoma." (PMID 34462486, 2021). "Of particular relevance to our work, high expression of GABRA3 transcripts, or its encoded α3 protein, is correlated with poor patient outcome in neuroblastoma and lung adenocarcinoma." (PMID 33187258, 2020). "Herein, we show that high GABRA3 protein expression in lung adenocarcinoma correlated positively with disease stage, lymphatic metastasis status and poor patient survival." (PMID 27081042, 2016). "Additionally, diffuse membrane and the cytoplasmic expression of GABRA3 protein were observed in both primary lung adenocarcinoma and matched brain-metastatic tissue sections." (PMID 39335139, 2024). "Likewise, knocking down GABRA3 expression in our previously established primary Am1010 cells, derived from muscle metastases of a human lung adenocarcinoma, inhibited invasive activity in Transwell assays." (PMID 27081042, 2016). "A previous study shows that Gabra3 induced MMP-2 and MMP-9 expression through activating the JNK signaling pathway, which enhanced lymphatic metastasis in lung adenocarcinoma." (PMID 29078789, 2017). "In addition, GABRA3 induced MMP-2 and MMP-9 expression through activation of the JNK/AP-1 signaling pathway, which enhanced lymphatic metastasis by lung adenocarcinoma both in vitro and in vivo." (PMID 27081042, 2016).
Anxiety (4 papers, 2014 to 2021). Intense feelings of nervousness, tension, or panic often arise in response to interpersonal stresses. "Interestingly, ad libitum intake of a normal diet reversed the decreased expression of Gabra2 but also induced an increase in anxiety-like behavior; in addition, persistently reduced hippocampal expression of Gabra3 was observed in the FMCD group." (PMID 25144567, 2014).
epilepsy (4 papers, 2017 to 2026). A brain disorder characterized by episodes of abnormally increased neuronal discharge resulting in transient episodes of sensory or motor neurological dysfunction, or psychic dysfunction. "First, GABRA3 is the only epilepsy-associated GABAA receptor gene that is located on the X chromosome." (PMID 41289009, 2026). "In GOF GABRA3 variants, affected individuals present with moderate-to-severe epilepsy in all hemizygous males and most heterozygous female carriers." (PMID 41289009, 2026). "Disorders of GABRA3, the only epilepsy-associated GABAA receptor subunit gene on the X chromosome, have eluded clinical clarity due to ambiguous inheritance patterns and variable phenotypes." (PMID 41289009, 2026). "Despite its recognition as an epilepsy-associated gene, many aspects of GABRA3 remain obscure." (PMID 41289009, 2026). "Modules with paired seeds related to the epilepsy phenotype (GABRA3-GABRB1, GRIN2A-GRIN2B and SCN1A-SCN2A) were enriched in terms such as long-term potentiation, chemical synaptic transmission, among others and showed selective expression in deep cortical neurons." (PMID 36699383, 2022). "Although GABRA3 is not yet routinely included in smaller epilepsy gene panels, the increasing adoption of exome and genome sequencing will enhance the detection of pathogenic GABRA3 variants in the future." (PMID 41289009, 2026).
lung carcinoma (4 papers, 2013 to 2020). "The GABAA receptor subunit GABRA3 is reportedly upregulated in lung cancer." (PMID 27081042, 2016). "Recent evidence suggests that dysregulated Gabra3, one of of the subunits of the GABA receptor, can regulate cancer development, such as lung cancer." (PMID 29078789, 2017). "Furthermore, our clinical data analysis showed that both GABAA receptors (GABRA3) and GABAB receptor (GABBR2) genes were significantly expressed in the early pathological stage (stage I and II) of the lung cancer patients, and the expression was gone in stage III and IV." (PMID 23617850, 2013).
autism (3 papers, 2013 to 2022). Persistent deficits in social interaction and communication and interaction as well as a markedly restricted repertoire of activity and interest as well as repetitive patterns of behavior. "Focusing on just the top 1% in the two validation datasets, given their high correlation, we identified several other genes that have been implicated in autism and synaptic transmission including GABRA3, GABRA5 and GABRB1, all of which encode subunits of the GABA receptor." (PMID 29483624, 2019). "Furthermore, the downregulation of the GABRA3 gene was observed in the cortex of patients with autism." (PMID 35222660, 2022).
depression (3 papers, 2011 to 2023). "Mice with overall deletion of the GABRA3 gene have more depression-related behaviors." (PMID 37140907, 2023). "Some well-known depression candidate genes that do not have scores greater than 0.01 in the HuGE genes are included in our DEPgenes, such as DBH, CHRNA7, and GABRA3, which were all ranked in the top list of DEPgenes." (PMID 21494644, 2011).
hepatocellular carcinoma (2 papers, 2016 to 2025). A malignant tumor that arises from hepatocytes. "Gene GABRA3 has been associated with TMB and shown to promote antitumor immunity in hepatocellular carcinoma based on multi-omics analysis." (PMID 41357226, 2025).
melanoma (2 papers, 2019 to 2021). A malignant, usually aggressive tumor composed of atypical, neoplastic melanocytes. "Interestingly, examination of transcriptomic (RNA-seq) and methylomic (Infinium methylation assay) data from the Cancer Genome Atlas (TCGA), revealed a significant association between expression of CT-GABRA3 and hypermethylation of the downstream GABRA3 promoter in melanoma." (PMID 34462486, 2021). "Intriguingly, DNA hypermethylation of the GABRA3 promoter was observed specifically in the melanoma cells where the promoter of CT-GABRA3 was hypomethylated and active, and a comparable trend was observed among 10 melanoma tissue samples." (PMID 34462486, 2021). "An intriguing observation was that in the melanoma cell lines where we detected hypomethylation and activation of MAGEA6/CT-GABRA3, the promoter of GABRA3 exhibited marked hypermethylation." (PMID 34462486, 2021).